KRAS (KRas proto-oncogene, GTPase)
Diseases named in the same sentence as KRAS in open-access papers (continued):
Sharing a sentence is not in itself a finding about the gene and the disease.
cancer (continued). "GSK-3 has clear pro-tumor actions in many cancers, notably including KRAS-mutant tumors." (PMID 35911672, 2022). "The positive correlation of DX2 and KRAS levels in cancer cells and patients suggests that the interaction interface may provide a target for suppressing KRAS-driven tumorigenesis." (PMID 35546148, 2022). "While KRAS is the most commonly observed mutation in PDAC, dysregulation of and mutations in other RAS/RAF/MAPK pathway members are frequently observed in other cancer types." (PMID 35454872, 2022). "Based on integrated analyses of RNAi- and CRISPR-mediated functional genomics, we identified NOP56 as a novel metabolic dependency of KRAS-mutant cancer by regulating homeostasis of reactive oxygen species (ROS) that plays a well-established role in mutant KRAS-induced tumorigenesis." (PMID 35039048, 2022). "Moreover, some non-coding RNAs have been found to participate in the pathogenesis of cancer through interacting with KRAS." (PMID 35139853, 2022). "Similarly, 249C significantly increased apoptosis in KRAS-mutant cancer cells as compared to KRAS WT cells." (PMID 35879364, 2022). "Intriguingly, in contrast to macropinocytosis, exosomal delivery of metabolites to cancer cells is independent of KRAS mutations." (PMID 36612058, 2022). "A synergistic cytotoxic impact induced by the ATO and VC combination indicates that surpassing an oxidative threshold in KRAS-mutant cancer cells affects the redox-sensitive cellular systems including the most vulnerable mitochondrial oxidative phosphorylation system (OXPHOS) complexes." (PMID 36359850, 2022). "Although KRAS mutations are undruggable and no anti-KRAS therapies exist for them, some inhibitors show effects against cancers." (PMID 35409064, 2022). "This suggests that targeting ILK in KRAS mutant cancer cells might show less impact in sensitizing cancer cells to immune cell cytotoxicity." (PMID 35692780, 2022). "Ross investigates and therapeutically targets KRAS mutants in cancer and RASopathies." (PMID 35234864, 2022). "Furthermore, BCL6 knockdown dramatically reduced the clonogenic growth of various KRAS-mutant cancer cell lines." (PMID 36377663, 2022). "KRAS cancers are a typical example of oncogene “addiction” also known as KRAS dependency." (PMID 36359850, 2022). "KRAS G12R mutated cancers with co-occurring PI3K pathway mutations vs. those without PI3K pathway genetic alterations harbored significantly more SMAD4 gene defects (83.3% vs. 11.8%, P = .0034)." (PMID 36124727, 2022). "In conclusion, our findings reveal novel insights into KRAS expression and its biological functions in diverse cancer types, indicating that KRAS could serve as a prognostic biomarker and is associated with immune infiltrates." (PMID 35563733, 2022). "Moreover, the abnormal level of KRAS showed substantial correlations with drug–gene interactions in different cancer types." (PMID 35563733, 2022). "In contrast, neither KRAS nor PIK3CA mutated cancers showed differences in NNMT expression relative to respective wild type tumors." (PMID 35177765, 2022). "We next turned to KRAS G12C cancer cell lines to test whether treatment with ARS1620 would result in native processing and loading of haptenated K-Ras peptides into MHC-I complexes in live cells." (PMID 36099883, 2022). "The glucose-lowering drug metformin exerted anti-cancer effect and enhanced efficacy of chemotherapy in NSCLC with KRAS/STK11 co-mutation, yet it is unknown whether metformin may enhance ICI efficacy in STK11 mutant NSCLC." (PMID 35281267, 2022).
cancer (continued). "We therefore examined whether we could rescue the loss of cell viability caused by Gln deprivation or utilization and ACLY inhibition in KRas-driven cancer cells with α-KG." (PMID 36269753, 2022). "BCL6 inhibition impedes the growth of KRAS-mutant cancer cells in vitro." (PMID 36377663, 2022). "Therefore, GPR110 can induce EMT and CSC by activating the KRAS pathway, suggesting that it can regulate KRAS hyperactivity that contributes to cancer progression by targeting GPR110." (PMID 35614051, 2022). "Following that, we looked at the prognostic values of KRAS in different cancer types." (PMID 35563733, 2022). "To better understand the KRAS-related functions in tumorigenesis and cancer immunity, we further explored the molecular characteristics of genes by utilizing gene set enrichment analysis in four types of cancers (LUAD, LUSC, BRCA, and PAAD)." (PMID 35563733, 2022). "The mutated KRAS is activated and unable to create normal RAS protein, causing the intracellular signal to be disrupted, resulting in uncontrolled cell proliferation and cancer." (PMID 35975176, 2022). "Moreover, COMP7 treatment attenuated the clonogenic growth of various KRAS-mutant cancer cell lines, eliciting a general inhibitory effect." (PMID 36377663, 2022). "This retrospective review of NSCLC genomics data from the BC Cancer Genomic Lab Oncopanel Dataset summarizes the frequency of actionable driver mutations (EGFR, KRAS G12C, MET Exon 14 skip, ALK fusion, and ROS1 fusion), PDL-1 expression, and treatment wait times among five health authorities." (PMID 36661661, 2022). "Many human cancers are driven by mutant KRAS, but its effects on noncoding RNA are unclear." (PMID 35858545, 2022). "The Gly-12 codon in KRAS (GGT) is a site of multiple base changes observed in cancer." (PMID 35864332, 2022). "Cancers driven by mutant KRAS proteins are considered refractory to most therapies." (PMID 36479072, 2022). "It is likely that the targeting of specific KRAS-mutant cancers in combination with other established cancer drugs or treatments such as radiation or chemotherapy might lead to effective therapeutics." (PMID 36359850, 2022). "Therefore, a complex functional network between different classes of non-coding RNAs is involved in the regulation of KRAS levels in cancers." (PMID 35139853, 2022). "Moreover, a synergistic action of ATO and VC in killing KRAS-mutant cancer cells (the human SW620 and LOVO colorectal adenocarcinoma cell lines) has also been described by another group." (PMID 36359850, 2022). "Of the three subfamily members HRAS, KRAS and NRAS, KRAS is the most frequently mutated in cancers." (PMID 35586192, 2022). "Because the central role of KRAS is mediated by diverse cellular processes that not only occur in cancer cells but also involve the TME, this versatility of KRAS effector pathways is destined to dictate diverse adaptions that can be undertaken under treatment pressure." (PMID 36483040, 2022). "However, unlike NSCLC with less frequent oncogenic drivers (e.g., EGFR, ALK, MET1, and ROS1) that respond significantly to selective kinase inhibitors, effective therapies specifically targeting KRAS-mutant cancers remains a challenge." (PMID 35039048, 2022). "Our results imply that conventional cell-based screens for the discovery and development of novel KRAS blockers might be suboptimal, and that IL-1β inhibition may be specifically effective against KRAS-mutant cancers." (PMID 35327394, 2022).
cancer (continued). "Notably, the KRAS (Kirsten rat sarcoma viral oncogene) isoform represents 75% of RAS mutant cancers." (PMID 35251972, 2022). "This implies that the “open conformation” may be a convergent point for survival signaling in KRAS-driven cancer, and agents locking this “open conformation” may theoretically block KRAS-dependent signaling." (PMID 36291766, 2022). "Moreover, resistance to lapatinib and nilotinib treatment alone was associated with KRAS mutation phenotype in both COREAD and Pan-Cancer (Excel sheet, sub-sheet 3.5), emphasizing the value of combinatorial regime against KRAS mutant tumors." (PMID 35664781, 2022). "Based on our study, KRAS may be a reliable prognostic biomarker for cancer patients in the course of diagnosis and treatment." (PMID 36330448, 2022). "Other inhibitors, ARS-853 and AMG 510, target specifically KRAS G12C mutation and do not act on the KRAS G12V or G12D mutants occurring more frequently in human cancers." (PMID 36359850, 2022). "which blocked KRAS activated signaling pathway and induced apoptosis of cancer cells in vitro." (PMID 36465350, 2022). "The approach of developing agents for each KRAS mutation necessitates an array of drugs to be developed and does not address cancers with dysregulation of non-mutant KRAS." (PMID 35216221, 2022). "We observed statistically significant shortening of telomeres in cancer tissue, irrespective of age group, gender, location (right/left sided), pathological diagnosis, staging, grading, mutational status (KRAS rs112445441 and BRAFv600E) or MSI status." (PMID 35565379, 2022). "Furthermore, we aim to highlight the role of autophagy in cancer and how KRAS mutants modulate autophagy." (PMID 35883626, 2022). "Taking it into account, a synergy of the ATO and VC combination in killing KRAS-mutant cancer cells might take place by the two-step actions." (PMID 36359850, 2022). "Thus, it is still high significance to further explore dynamics changes of KRAS by using rational conformational sampling technology for efficiently understanding the role of KRAS in drug targets toward cancer treatments." (PMID 35425180, 2022). "Pan-inhibitors that inhibit b-RAF proto-oncogene (BRAF) and c-RAF proto-oncogene (CRAF) as well as not activating the MAPK pathway in cancers harboring KRAS mutations are being generated and show in vitro promising results." (PMID 33801965, 2021). "Taselisib is being tested in a phase II study in patients with different cancers (excluding breast) with PIK3CA mutation but without KRAS mutation or PTEN loss." (PMID 33801659, 2021). "The present findings suggest that the targeted inhibition of downstream effectors (e.g., RAF, MEK, ERK, PI3K, AKT, and mTOR) or combinations thereof may be a more rational and effective approach for the treatment of cancers driven by KRAS Q61H." (PMID 34725361, 2021). "Growing evidence exists of the role of small non-coding RNA, particularly micro-RNA (miRNA’s), in controlling the key biological process, including deciding the fate of cancer treatment, such as the tumor-suppressive effect of miR-193a-3p in lung cancer through targeting KRAS expression." (PMID 34299137, 2021). "Inhibitors targeting BRAF, MEK, or ERK have been developed to block KRAS signaling in cancer." (PMID 34947990, 2021). "Thus, KRAS inhibition in cancer cells can shift the balance from an immunosuppressive state to a microenvironment favoring effective antitumor activity and can sensitize tumors to checkpoint inhibitor therapy." (PMID 33777798, 2021).
cancer (continued). "Collectively, these findings improve our understanding of how exactly KRAS mutant cancer cells upregulate expression of AATs as upstream stimulants, which is clinically relevant, since they are overexpressed in multiple cancers and therefore represent attractive therapeutic targets." (PMID 34003553, 2021). "We found that KRAS expression was down-regulated in CRC tissues in four stages of the cancer." (PMID 33825830, 2021). "As part of a study focused on overriding mtRAS, we expanded the application of this series of compounds to various cancer cells harboring KRAS-G12D (AsPC-1), KRAS-G12V (SW480, DU-145), KRAS-G12C (H358), KRAS-G13D (MDA-MB-231), KRAS-Q61L (HT-29), and NRAS-Q61L (OCI-AML3)." (PMID 34956887, 2021). "KRAS mutations are often associated with resistance to targeted therapies and poor outcomes in patients with cancer; however, no selective KRAS inhibitor has yet been approved despite more than three decades of scientific effort." (PMID 34840814, 2021). "Indeed, in KRAS mutant cancer cells KRASG12C inhibition with ARS-853 was increased by the combination with EGFR inhibitors." (PMID 33777798, 2021). "Since BKA-073 is able to induce apoptosis by activation of Bak via facilitating its oligomerization in vitro and in vivo, we were interested in testing whether BKA-073 is effective for the treatment of mutant KRAS-driven cancer." (PMID 34373755, 2021). "The search for efficacious inhibitors of all other mutant KRAS-driven cancers continues." (PMID 35024121, 2021). "NRAS is, together with KRAS, part of the GTPase family of genes that are often activated in cancer." (PMID 34615983, 2021). "have demonstrated that BET inhibitors might enhance the efficacy of MEK inhibitors in KRAS-mutant cancers." (PMID 35004317, 2021). "Thus, we believe that communications regarding the biochemical properties and biological functions of KRAS protein will accelerate the development of more effective cancer therapies." (PMID 33917906, 2021). "Nonetheless, the cell-active molecules identified here validate a unique inhibitory epitope on KRAS and thus provide valuable molecular templates for the development of therapeutics that are desperately needed to address KRAS-driven cancers – some of the most treatment-resistant human malignancies." (PMID 35024121, 2021). "Therefore, understanding networks downstream of KRAS and how they link to the cancer phenotype is a key future goal." (PMID 33691728, 2021). "Accumulated evidence unearthed by research studies suggests that solving previously known adverse drug reactions might facilitate the development of novel drugs with significant impacts on KRAS-driven cancers." (PMID 33917906, 2021). "Finally, we addressed the importance of Phafin2 in a physiological process relying on macropinocytosis, the scavenging of extracellular proteins by KRAS-transformed cancer cells." (PMID 34772942, 2021). "Targeting mutant KRAS remains a “holy grail” in cancer research." (PMID 34573384, 2021). "However, KRAS mutant cancer cells develop resistance against therapeutic agents through altered metabolic pathways." (PMID 34003553, 2021). "First, our study is mainly based on bioinformatics analysis, and more experimental studies are needed to investigate how KRAS may regulate cancer cell metabolism in PC." (PMID 34660806, 2021). "Oncogenic KRAS driven cancers require NF-κB anti-apoptotic signals involving c-Rel." (PMID 33959502, 2021).
cancer (continued). "KRAS mutant cancer cell lines were relatively more sensitive to KRAS genetic knockout." (PMID 34215850, 2021). "In addition, statin was recently shown to enhance the immunogenicity of KRAS-mutant cancer by inhibiting its prenylation." (PMID 34947990, 2021). "Further screening will be required to identify drug combinations that may optimally impact cancer stem-progenitor cell populations, leading to more effective treatments for KRAS mutant tumors." (PMID 34257283, 2021). "Although most of KRAS-mutant NSCLC are diagnosed in former or active smokers, KRAS mutations can also be detected in never smoker patients with early onset of cancer, thus its mutational state cannot be predicted on the basis of smoking history alone." (PMID 35004317, 2021). "Moreover, we also searched for mutant and wild type KRAS in exosomes released by the same cancer cell lines." (PMID 34811396, 2021). "Several MEK inhibitors have been tested in KRAS-mutated cancers and have not shown any clinical benefits." (PMID 34947990, 2021). "However, KRAS mutant tumors comprise a heterogeneous group of cancers and reported mechanisms of cellular radioresistance appear highly variable, consistent with the notion of intertumoral heterogeneity." (PMID 34778082, 2021). "It is shown that knockdown of STK33 leads to a decrease in viability of KRAS mutant cancer cells." (PMID 34955846, 2021). "In this review, we summarize the approaches that have been applied over the years to inhibit the membrane localization of KRAS in cancer and propose a new anti-KRAS strategy that could be used in clinic." (PMID 34947990, 2021). "Cancer metastasis is a complex phenotype and collective migration assessments alone are not sufficient to capture the differences in metastatic potential of the KRas and KRas/PTEN−/− cells." (PMID 33986306, 2021). "In terms of biological functions, these modules are correlated with several cancer hallmarks and pathways, including Myc targets, E2F targets, cell cycle, inflammation/immunity-related pathways, androgen/oestrogen response, KRAS signalling, DNA repair and epithelial-mesenchymal transition (EMT)." (PMID 34872564, 2021). "Despite its high prevalence and importance in the development of cancer, efforts to effectively target KRAS have long been futile as a consequence of micromolar GTP concentrations in cells (~0.5 mmol/L) combined with a picomolar affinity (dissociation constant at ~10-10 mol/L) of KRAS for GTP." (PMID 35004309, 2021). "In most cases, tumors samples with a specific KRAS allele did not, on average, have a higher probability of obtaining that mutation than other tumors of the same cancer type." (PMID 33753749, 2021). "The G12C mutation is a common mutation in the Ras proto-oncogenes (HRAS, KRAS, and NRAS) and, therefore, might be a suitable mutation to target various types of cancer and their causes." (PMID 35062725, 2021). "In a study conducted in different cancer cell lines, KRAS mutation was not correlated with the dependance to autophagy." (PMID 33777798, 2021). "However, the identities of the amino acid transporters (AATs) that are prominently upregulated in KRAS mutant cancer cells, and the mechanism regulating their expression have not yet been systematically investigated." (PMID 34003553, 2021). "These evidences fully define the increase pyrimidine synthesis flux in KRAS mutant cancer cell." (PMID 34123854, 2021). "At present, few therapies are available for patients with KRAS-driven cancers." (PMID 34503246, 2021). "Meanwhile, KRAS is also involved in the regulation of noncoding RNAs in some cancers." (PMID 34512755, 2021). "Members of the rat sarcoma (RAS) oncogene family, including Kirsten-RAS (KRAS), Harvey-RAS (HRAS), and neuroblastoma-RAS (NRAS), exhibit the highest mutation frequency in human cancers, with associated mutations being identified in approximately 30% of all cancers." (PMID 34512755, 2021).